HSP90AA1 (heat shock protein 90 alpha family class A member 1)
Description:
Molecular chaperone that promotes the maturation, structural maintenance and proper regulation of specific target proteins involved for instance in cell cycle control and signal transduction. Undergoes a functional cycle that is linked to its ATPase activity which is essential for its chaperone activity. This cycle probably induces conformational changes in the client proteins, thereby causing their activation. Interacts dynamically with various co-chaperones that modulate its substrate recognition, ATPase cycle and chaperone function. Engages with a range of client protein classes via its interaction with various co-chaperone proteins or complexes, that act as adapters, simultaneously able to interact with the specific client and the central chaperone itself. Recruitment of ATP and co-chaperone followed by client protein forms a functional chaperone. After the completion of the chaperoning process, properly folded client protein and co-chaperone leave HSP90 in an ADP-bound partially open conformation and finally, ADP is released from HSP90 which acquires an open conformation for the next cycle. Plays a critical role in mitochondrial import, delivers preproteins to the mitochondrial import receptor TOMM70. Apart from its chaperone activity, it also plays a role in the regulation of the transcription machinery. HSP90 and its co-chaperones modulate transcription at least at three different levels. In the first place, they alter the steady-state levels of certain transcription factors in response to various physiological cues. Second, they modulate the activity of certain epigenetic modifiers, such as histone deacetylases or DNA methyl transferases, and thereby respond to the change in the environment. Third, they participate in the eviction of histones from the promoter region of certain genes and thereby turn on gene expression. Binds bacterial lipopolysaccharide (LPS) and mediates LPS-induced inflammatory response, including TNF secretion by monocytes. Antagonizes STUB1-mediated inhibition of TGF-beta signaling via inhibition of STUB1-mediated SMAD3 ubiquitination and degradation. Mediates the association of TOMM70 with IRF3 or TBK1 in mitochondrial outer membrane which promotes host antiviral response. (Microbial infection) Seems to interfere with N.meningitidis NadA-mediated invasion of human cells. Decreasing HSP90 levels increases adhesion and entry of E.coli expressing NadA into human Chang cells; increasing its levels leads to decreased adhesion and invasion.
Synonyms: HSP86; LAP-2; HSP90A; HSPC1; HSPCA; Hsp89; Hsp90; FLJ31884; HSP90N; EL52; HEL-S-65p; HSP89A; HSPCAL1; HSPCAL4; HSPN; Hsp103; LAP2
Tractability: Small molecule: a drug acting on it is in phase 2 or 3 trials; a structure with a bound ligand is known; a high-quality ligand is known; it has a high-quality binding pocket; it belongs to a druggable protein family. Antibody: UniProt places it where antibodies can reach, with high confidence; its Gene Ontology location is reachable by antibodies, with high confidence. PROTAC: UniProt records ubiquitination sites on it; ubiquitination databases record sites on it; its protein half-life has been measured; a small molecule that binds it is known. Other modalities: a drug acting on it is in phase 2 or 3 trials.
Target class: Other cytosolic protein
Chemical probes: BIIB021 (high quality), NMS-E973, ONALESPIB (high quality), PD080865, PD081779, PD083270, PD083458, PD083632, PD083785, PD084145, PD084766, PD134555, PD134556, PD134557, PD134558, PD134559, luminespib (high quality)
Gene: Protein-coding gene on chromosome 14 (102,080,738 to 102,139,699, reverse strand). Ensembl gene ENSG00000080824.
Subcellular location: Nucleus; Cytoplasm; Melanosome; Cell membrane; Mitochondrion
Subcellular location (Human Protein Atlas): Cytosol; Nucleoplasm
Pathways (Reactome):
Disease: Assembly and release of respiratory syncytial virus (RSV) virions; Constitutive Signaling by EGFRvIII; Constitutive Signaling by Ligand-Responsive EGFR Cancer Variants; Constitutive Signaling by Overexpressed ERBB2; Dengue virus activates/modulates innate and adaptive immune responses; Drug resistance in ERBB2 TMD/JMD mutants; Potential therapeutics for SARS; Resistance of ERBB2 KD mutants to AEE788; Resistance of ERBB2 KD mutants to afatinib; Resistance of ERBB2 KD mutants to lapatinib; Resistance of ERBB2 KD mutants to neratinib; Resistance of ERBB2 KD mutants to osimertinib; Resistance of ERBB2 KD mutants to sapitinib; Resistance of ERBB2 KD mutants to tesevatinib; Resistance of ERBB2 KD mutants to trastuzumab; Respiratory syncytial virus genome replication; SARS-CoV-2 activates/modulates innate and adaptive immune responses; Signaling by ERBB2 ECD mutants; Signaling by ERBB2 KD Mutants; Signaling by ERBB2 TMD/JMD mutants; Uptake and function of diphtheria toxin; vRNP Assembly
Signal Transduction: Downregulation of ERBB2 signaling; Drug-mediated inhibition of ERBB2 signaling; ESR-mediated signaling; Estrogen-dependent gene expression; Extra-nuclear estrogen signaling; RHOBTB2 GTPase cycle; Signaling by ERBB2; VEGFA-VEGFR2 Pathway; VEGFR2 mediated vascular permeability
Cell Cycle: AURKA Activation by TPX2; Loss of Nlp from mitotic centrosomes; Loss of proteins required for interphase microtubule organization from the centrosome; Recruitment of NuMA to mitotic centrosomes; Recruitment of mitotic centrosome proteins and complexes; Regulation of PLK1 Activity at G2/M Transition; The role of GTSE1 in G2/M progression after G2 checkpoint
Cellular responses to stimuli: Attenuation phase; HSF1 activation
and 15 more pathways
Gene Ontology:
Molecular function: ATP binding; ATP hydrolysis activity; disordered domain specific binding; DNA polymerase binding; enzyme-substrate adaptor activity; GTPase binding; histone deacetylase binding; identical protein binding; MHC class II protein complex binding; nitric-oxide synthase regulator activity; protein binding; protein homodimerization activity; protein tyrosine kinase binding; RNA binding; scaffold protein binding; tau protein binding; TPR domain binding; ubiquitin protein ligase binding; AP-3 adaptor complex binding; ATP-dependent protein folding chaperone; CTP binding; dATP binding; GTP binding; mRNA binding; protein folding chaperone; and 5 more
Biological process: activation of innate immune response; cellular response to virus; chaperone-mediated protein complex assembly; neurofibrillary tangle assembly; positive regulation of defense response to virus by host; positive regulation of interferon-beta production; positive regulation of protein catabolic process; positive regulation of protein polymerization; protein import into mitochondrial matrix; protein maturation; protein stabilization; regulation of apoptotic process; regulation of protein ubiquitination; telomerase holoenzyme complex assembly; telomere maintenance via telomerase; cellular response to heat; chaperone-mediated autophagy; mitochondrial transport; nitric oxide metabolic process; positive regulation of nitric oxide biosynthetic process; positive regulation of telomere maintenance via telomerase; protein refolding; protein unfolding; regulation of protein localization; regulation of protein-containing complex assembly; and 27 more
Cellular component: cytoplasm; cytosol; extracellular exosome; HSP90-CDC37 chaperone complex; melanosome; membrane; mitochondrion; nucleus; plasma membrane; protein folding chaperone complex; protein-containing complex; axonal growth cone; dendritic growth cone; endocytic vesicle lumen; extracellular region; ficolin-1-rich granule lumen; lysosomal lumen; myelin sheath; neuronal cell body; nucleoplasm; perinuclear region of cytoplasm; secretory granule lumen; apical plasma membrane; basolateral plasma membrane; brush border membrane; and 6 more
Genetic constraint (gnomAD): Loss-of-function variants: 16 observed, 67.17 expected, observed/expected ratio (o/e) 0.24, 90% interval 0.16 to 0.36. The synonymous counts are far from expectation, so gnomAD's model fits this gene poorly and the ratio says little. Missense variants: 583 observed, 798.38 expected, observed/expected ratio (o/e) 0.73, 90% interval 0.68 to 0.78. Synonymous variants: 433 observed, 270.22 expected, observed/expected ratio (o/e) 1.6, 90% interval 1.48 to 1.74.
Homologues: Orthologues: macaque HSP90AA1 (100% identical), chimpanzee HSP90AA1 (99% identical), guinea pig HSP90AA1 (99% identical), dog HSP90AA1 (99% identical), rat Hsp90aa1 (99% identical), mouse Hsp90aa1 (99% identical), pig HSP90AA1 (99% identical), tropical clawed frog hsp90aa1 (93% identical), zebrafish hsp90aa1.2 (91% identical), zebrafish hsp90aa1.1 (85% identical), Drosophila melanogaster Hsp83 (78% identical), Caenorhabditis elegans hsp-90 (74% identical). Paralogues in human: HSP90AB1 (86% identical), HSP90B1 (48% identical), TRAP1 (30% identical).
Diseases named in the same sentence as HSP90AA1 in open-access papers:
HSP90AA1 is named in the same sentence as 212 diseases in open-access papers, as found by Europe PMC text mining. Sharing a sentence is not in itself a finding about the gene and the disease. The quoted sentences say what the papers report.
breast cancer (51 papers, 2008 to 2026). A primary or metastatic malignant neoplasm involving the breast. "In humans, Hsp90aa1 is associated with poor prognosis in cancers such as leukemia and breast cancer." (PMID 39769404, 2024). "To explore the effect of breast cancer prognosis-related genes on tumor cell progression in the model, we selected the gene with the highest risk factor (HSP90AA1) for validation." (PMID 38263419, 2024). "Plasma HSP90AA1 has been found to predict the risk of breast cancer incidence and distant metastasis." (PMID 38420434, 2024). "there is a considerable body of evidence that shows plasma levels of HSP90AA1 has clinical benefit in prediction of onset and risk of metastasis in breast cancer patients." (PMID 35290401, 2022). "In this study, we aimed to examine the diagnostic value of plasma HSP90AA1 in breast cancer by using an online database and clinical parameters." (PMID 34109171, 2021). "We aimed to develop and validate a comprehensive nomogram containing pre-treatment plasma HSP90AA1 to predict the risk of breast cancer onset and metastasis." (PMID 34109171, 2021). "HSP90AA1 is a new disease and metastasis risk evaluation index for breast cancer patients is essential." (PMID 34109171, 2021). "HSP90AA1 raised net clinical benefit of breast cancer onset and metastasis risk prediction nomogram in a range of risk thresholds (5–92%) and (1–90%)." (PMID 34109171, 2021). "Researchers revealed that pretreatment plasma HSP90AA1 combined with other markers could conveniently predict the risk of breast cancer onset and metastasis." (PMID 40299459, 2025). "In another study, a nomogram model constructed by database and clinical parameter analyses to evaluate the prognosis and metastasis risk of breast cancer revealed pretreatment plasma HSP90AA1 combined with other biomarkers to easily predict the risk of breast cancer incidence and metastasis." (PMID 38713284, 2024). "Using established biomarkers for breast cancer which are currently available in clinical practice, we first developed a predictive model including HSP90AA1, which can be used to calculate breast cancer risk for breast disease and risk of distant metastasis in breast cancer." (PMID 34109171, 2021). "Our study revealed that pretreatment plasma HSP90AA1 combined with other markers could conveniently predict the risk of breast cancer onset and metastasis." (PMID 34109171, 2021). "For example, the HSP90AA1 gene stabilizes the NME1 protein in breast cancer cells, and its overexpression protects endogenous NME1 protein from degradation, leading to reduced metastasis formation in vitro and in vivo." (PMID 41507145, 2026). "HSP90AA1 mRNA expression is up-regulated in breast cancer tissues, and its high expression is strongly correlated with the short overall and progression-free survival of patients." (PMID 40230723, 2025). "We observed the HSP90AA1 expression level in several breast cancer cells utilizing qRT-PCR and Western blot and selected MDA-KB231 and MCF-7 cell lines for subsequent experimental validation." (PMID 38263419, 2024). "According to a previous study, high HSP90AA1 expression was an independent factor correlated with mortality in breast cancer patients (triple-negative and human epidermal growth factor receptor 2-negative/estrogen receptor-positive subtypes)." (PMID 35330393, 2022). "Our findings of gene expression and breast cancer prognosis were consistent with the previous evidence for HSP90AA1, ADCY4, and GNG7." (PMID 35729536, 2022). "Consistent with our results, higher expression of HSP90AA1 was reported to unfavourably affect breast cancer patient survival." (PMID 35273218, 2022). "In a multi-center clinical study of 1,558 patients (39 cases of breast cancer), plasma HSP90AA1 can be used as a biomarker for cancer." (PMID 34109171, 2021). "It was found that in some ELISA-negative breast cancer patients, the secretion level of plasma Hsp90AA1 detected by western blotting was higher than the critical value." (PMID 34109171, 2021).
breast cancer (continued). "In summary, our results indicated that although gene expression levels of HSP90AA1, HSP90AA2, HSP90AB1, HSP90B1, and TRAP1 were upregulated in breast cancer patients, only the expression of HSP90AA1 was related to the tumor stage and prognostic survival." (PMID 34109171, 2021). "HSP90AA1 is an intracellular gene that is actively expressed in breast cancer cells—high levels of which correlate with a low chance of survival." (PMID 33432018, 2021). "As a new target for cancer therapy, HSP90AA1 is highly expressed in a variety of malignant tumors, including breast cancer, endometrial cancer, ovarian cancer, colon cancer, lung cancer and prostate cancer." (PMID 33491737, 2021). "We also observed a significant correlation between the expression of HSP90AA1 and tumor stage in breast cancer patients." (PMID 34109171, 2021). "HSPs themselves can be prognostic factors in breast cancer and especially oncogenic properties of HSP90AA1 correlated with aggressive clinicopathological features and resistance to the treatment." (PMID 34783649, 2021). "Here, we present a list of seven putative genes that are modulated by Rsv in breast cancer in the context of cotreatment with Doxo: HSP90AA1, CCND1, CDH1, ESR1, MAPK3, PTPN11, and RPS6KB1." (PMID 33204396, 2020). "Herein, using The Cancer Genome Atlas and KM plotter database, we showed strong association between expression of at least six HSP-encoding genes (namely: HSPA2, DNAJC20, HSP90AA1, CCT1, CCT2 and CCT6A) and survival of breast cancer patients." (PMID 31101846, 2019). "RT-qPCR revealed that Hsp90AA1 and Hsp90AB1 mRNA levels increased in breast cancer, consistent with TCGA data." (PMID 31921692, 2019). "In this study, we identified HSP90AA1 gene encoding HSP90 alpha protein, the inducible isoform of HSP90, among four most significant factors of poor prognosis in breast cancer." (PMID 31101846, 2019). "Collectively, these results suggest that high expression of HSPA2 and DNAJC20 is associated with low-risk breast cancer, whereas high expression of HSP90AA1, CCT1, CCT2 and CCT6A correlates with high-risk breast cancer." (PMID 31101846, 2019). "Not surprisingly, we also observed strong correlation between HSP90AA1 expression and poor survival of breast cancer patients based on data from two databases." (PMID 31101846, 2019). "We found that high-level expression of HSP90AA1 independently led to higher risk of death from breast cancer in TNBC, while HSP90AB1 caused poor survival among patients with the HER2-/ER+ breast cancer subtype through increased risk of distant metastasis." (PMID 22510516, 2012). "In addition, a comprehensive bioinformatics analysis of breast cancer exosomes revealed Hsp90AA1 as a novel hub gene in the exosomal proteins derived from human breast cancer cells." (PMID 38255948, 2024). "However, the specific mechanisms by which HSP90AA1 promotes its proliferation in breast cancer and how it affects immunogenic cell death through immune modulation still warrant investigation." (PMID 38263419, 2024). "The growth hormone prolactin induces HSP90AA1 expression in breast cancer cells through STAT5." (PMID 36139005, 2022). "In the present work, it also became apparent that HSP90AA1 may has a role in prediction of response to therapy in breast cancer." (PMID 35290401, 2022). "The OS of breast cancer patients with high HSP90AA1 expression was low." (PMID 34109171, 2021). "The mRNA levels of HSP90AA1 in breast cancer tissues were higher than those in normal tissues." (PMID 34109171, 2021). "Next, we investigated the significance of HSP90AA1 levels in the metastasis of breast cancer." (PMID 34109171, 2021). "HSP90AA1 was significantly elevated in breast cancer patients (p = 6.807e-07; Wilcoxon test)." (PMID 34109171, 2021). "The results indicated that HSP90AA1 was not a decisive factor in diagnosing metastasis in breast cancer; however, it improved diagnostic accuracy." (PMID 34109171, 2021).